IFFO2 (intermediate filament family orphan 2)
Tractability: Antibody: the Human Protein Atlas places it where antibodies can reach. PROTAC: ubiquitination databases record sites on it.
Gene: Protein-coding gene on chromosome 1 (18,904,280 to 18,956,676, reverse strand). Ensembl gene ENSG00000169991.
Subcellular location (Human Protein Atlas): Nucleoplasm; Plasma membrane
Genetic constraint (gnomAD): Loss-of-function variants: 15 observed, 35.76 expected, observed/expected ratio (o/e) 0.42, 90% interval 0.28 to 0.65. The upper end of that interval is the gene's LOEUF score, 0.65, which puts it in group 2 of 6, group 1 being the genes least tolerant of losing a copy. Missense variants: 451 observed, 504.77 expected, observed/expected ratio (o/e) 0.89, 90% interval 0.83 to 0.97. Synonymous variants: 232 observed, 203.74 expected, observed/expected ratio (o/e) 1.14, 90% interval 1.02 to 1.27.
Homologues: Orthologues: chimpanzee IFFO2 (100% identical), pig IFFO2 (98% identical), rat Iffo2 (96% identical), mouse Iffo2 (96% identical), guinea pig IFFO2 (94% identical), macaque IFFO2 (94% identical), dog IFFO2 (93% identical), tropical clawed frog iffo2 (72% identical), rabbit IFFO2 (64% identical), zebrafish iffo2b (61% identical), zebrafish iffo2a (58% identical). Paralogues in human: IFFO1 (59% identical).
Diseases named in the same sentence as IFFO2 in open-access papers:
IFFO2 is named in the same sentence as 5 diseases in open-access papers, as found by Europe PMC text mining. Sharing a sentence is not in itself a finding about the gene and the disease. The quoted sentences say what the papers report.
Glucose intolerance (1 paper, 2026). Glucose intolerance (GI) can be defined as dysglycemia that comprises both prediabetes and diabetes. "Similarly Itgb4 and Iffo2 DNAm correlate with glucose intolerance with Itgb4 upregulated in diabetic glomeruli and Iffo2 methylation associated with dietary glycaemic load." (PMID 41432313, 2026). "The predictor variables can be considered in three groups: those with insulin and glucose intolerance (Mbd2, Tnip1, Itgb4, and Iffo2), those with BMR (1010001N08RiK and Clvs2), and those associated with Tb (Calb2)." (PMID 41432313, 2026).
rhabdomyosarcoma (1 paper, 2025). A rare aggressive malignant mesenchymal neoplasm arising from skeletal muscle. "Similarly, in data from the NCBI, we found that the IFFO2 expression level in rhabdomyosarcoma patients with PAX3 and FOXO1 gene fusion, which is considered a predictor of adverse results in children with rhabdomyosarcoma, was lower than those in patients without PAX3 and FOXO1 gene fusion." (PMID 41359381, 2025).
cancer (2 papers, 2020 to 2026). A tumor composed of atypical neoplastic, often pleomorphic cells that invade other tissues. "The most downregulated circRNAs included both well-characterized cancer-associated circRNAs, such as CDR1as, as well as novel circRNAs, which were derived from host genes IFFO2, KRT1 and POF1B34." (PMID 32108138, 2020).
IFFO2 also shares sentences with these, for which no sentence is quoted: hepatocellular carcinoma (1 paper); liver disease (1).